NPIPB5 (nuclear pore complex interacting protein family member B5)
Tractability: Antibody: UniProt predicts a signal peptide or a membrane-spanning region.
Gene: Protein-coding gene on chromosome 16 (22,479,121 to 22,536,540, forward strand). Ensembl gene ENSG00000243716.
Subcellular location: Membrane
Subcellular location (Human Protein Atlas): Nucleoplasm
Gene Ontology:
Cellular component: membrane
Genetic constraint (gnomAD): Loss-of-function variants: 0 observed, 4.02 expected, observed/expected ratio (o/e) 0, 90% interval 0 to 0.74. That is too few expected variants to judge how well the gene tolerates losing a copy. Missense variants: 6 observed, 90.54 expected, observed/expected ratio (o/e) 0.0663, 90% interval 0.035 to 0.13. Synonymous variants: 0 observed, 33.37 expected, observed/expected ratio (o/e) 0, 90% interval 0 to 0.089.
Homologues: Paralogues in human: NPIPB11 (94% identical), NPIPB4 (92% identical), NPIPB13 (88% identical), NPIPB12 (81% identical), NPIPB3 (37% identical), NPIPB8 (29% identical), NPIPB9 (29% identical), NPIPB6 (28% identical), NPIPB2 (27% identical), NPIPB15 (27% identical), NPIPB7 (26% identical), NPIPA2 (24% identical), and 7 more.
Diseases named in the same sentence as NPIPB5 in open-access papers:
NPIPB5 is named in the same sentence as 5 diseases in open-access papers, as found by Europe PMC text mining. Sharing a sentence is not in itself a finding about the gene and the disease. The quoted sentences say what the papers report.
adenoma (1 paper, 2015). A neoplasm arising from the epithelium. "For the adenoma-specific mutations, we identified two genes (NPIPB5 and MUC2) with a substantial enrichment (P = 0.018 and 0.09, respectively)." (PMID 26336987, 2015).
clear cell renal cell carcinoma (1 paper, 2024). "Noclinical significance has been reported to this variant, but a recent studydescribed the gene NPIPB5 as a putative novel prognostic biomarkerfor clear cell renal cell carcinoma (Wang etal., 2022)." (PMID 38259032, 2024).
cancer (1 paper, 2021). A tumor composed of atypical neoplastic, often pleomorphic cells that invade other tissues. "Among the 54 cancer-related genes, DGKG, MPND, NPIPB5, PRR21, SGSM1, and TRIM67 displayed frameshift mutations." (PMID 34104084, 2021). "In addition, the present study revealed 6 cancer-related genes, DGKG, MPND, NPIPB5, PRR21, SGSM1, and TRIM67, which showed novel frameshift mutations." (PMID 34104084, 2021).
NPIPB5 also shares sentences with these, for which no sentence is quoted: keratoconus (1 paper); papillary renal cell carcinoma (1).